TNF (tumor necrosis factor)
Diseases named in the same sentence as TNF in open-access papers (continued):
Sharing a sentence is not in itself a finding about the gene and the disease.
tumor (continued). "Evidence for direct involvement of TNFα in DMBA carcinogenesis is provided by the observations that TNFα deficient mice are resistant to DMBA induced carcinogenesis and that neutralization of TNFα with a specific anti-TNFα antibody decreased tumor formation." (PMID 19784388, 2008). "This assistance involves the upregulation of IL-1, IL-6, IL-8, TNFα and MMPs that promote surrounding tissue destruction, leading to tumour invasion and ultimately metastasis." (PMID 19014637, 2008). "HUVEC monolayers were pre-activated with 25 ng/ml TNF-α for 6 h to upregulate the expression of adhesion molecules before the tumor migration assay." (PMID 18350162, 2008). "Histological examination of HT-29 xenografts revealed the presence of low concentrations of TNFα in tumours from control mice and AS602868-treated groups." (PMID 18182997, 2008). "In the present study, TNF-α was also used to activate NF-κB in HSG cells to mimic the local inflammatory response in the metastasized region, and some tumor cells were reported to produce TNF-α." (PMID 19091137, 2008). "The tumor cell microenvironment appears to govern the ability of IGF-1R to enhance or inhibit the pro-apoptotic activity of TNFα." (PMID 19784388, 2008). "Nuclear localization of NF-κB was evident by immunocytochemistry on CD133-selected tumor cells treated with tumor necrosis factor (TNF)α." (PMID 18492237, 2008). "The Rb tumor suppressor is cleaved by calpain during tumor necrosis factor-alpha (TNFα)-induced apoptosis in HeLa cells." (PMID 19098985, 2008). "We confirmed that some component of the secreted molecules was biologically active as tumor-specific stimulation of effector T cells or D5 exposed to IFN-γ or TNF-α induced the chemotaxis of the DJ2PM macrophage cell line in vitro." (PMID 18001476, 2007). "Our own data shows that chemokine secretion by D5 was markedly upregulated after stimulation with the type-1 cytokines, IFN-γ and TNF-α, expressed by therapeutic tumor-specific effector T cells." (PMID 18001476, 2007). "IL-2 and IL-13 were not correlated with PR status, whereas IL-1β, IL-6, IL-8, IL-10, IFN-γ, MCP-1, MIP-1β, TNF-α and, to a lesser extent, IL-4, IL-12 and G-CSF were more abundant in PR-negative tumours than in PR-positive ones." (PMID 17261184, 2007). "In chemical carcinogenesis, internal cytokines, such as interleukin (IL) 1α and tumour necrosis alpha (TNFα) contribute to tumour progression." (PMID 18045456, 2007). "We evaluated a panel of basal cytokines more commonly involved in the tumor control and progression (IL-1 beta, IL-6, IL-8, IL-10, IL-12, TNF-α) both in 144 healthy donors and in 55 patients affected by MRCC treated with IL-2 based regimens." (PMID 17953739, 2007). "Secretion of cytokines, particularly TNF-α, by activated macrophages is known to affect survival, growth and proliferation of the tumor." (PMID 17565690, 2007). "In this study we have examined PRL, TNF alpha and NO levels in plasma and in tumour homogenates during goserelin administration and, similar behaviour was observed." (PMID 18045456, 2007). "In this context, it is noteworthy that even the concentrations of IL-6 and TNF-α were found to be elevated in ARC in tumor-bearing rats." (PMID 18078524, 2007). "Probably directed in part by PGE2, based on reduced production of anti-tumor Th1 cytokines (TNFα, IFNγ and IL-2) and increased production of Th2 cytokines (IL-4, IL-10 and IL-6)." (PMID 19455240, 2007). "On the other hand, IL-2, IL-6, IL-8, IL-10, IFN-γ, MCP-1, MIP-1β, TNF-α and, to a lesser extent, IL-1β and IL-13 were significantly overexpressed in ER-negative tumours compared with ER-positive ones, with the greatest differences observed for IL-8 and MCP-1." (PMID 17261184, 2007). "It is therefore assumed that paclitaxel induces TNFα in stromal cells of tumour tissue, which in turn holds responsible for the increase of TP levels." (PMID 17640356, 2007).
tumor (continued). "The creation of triple helixes was used, for example, to repress the transcription of the tumor necrosis factor gene, which in turn inhibited the growth of TNF-dependent tumor cells." (PMID 18047709, 2007). "In the presence of autologous tumor cells these CTLs produced IFN-γ and TNF-α in tissue culture supernatant and were able to specifically lyse tumor cells in vitro as demonstrated in a chromium release assay." (PMID 17592641, 2007). "Tissue cytokine (IL-1β, IL-6, IL-8, and TNF-α) mRNA and protein levels were found at similar concentrations within tumour tissues with a chronic inflammatory cell infiltrate and tumour samples with lymphoid aggregates alone." (PMID 17088911, 2006). "In contrast, mRNA for IL-1β, IL-6, IL-8, and TNF-α were detected in tumour tissue at significantly elevated concentrations: IL-1β P<0.001; IL-6 P<0.001; IL-8 P<0.001; TNF-α P=0.006." (PMID 17088911, 2006). "TAMs can kill and phagocytose tumour cells and remove apoptotic and necrotic tumour cells by secreting lytic enzymes such as lysosomal enzymes, TNF-α and macrophage activation factor." (PMID 17026740, 2006). "They in turn produce various cytokines, such as tumor necrosis factor-α (TNF-α), IL-1, IL-4 and IL-6, which can induce apoptosis of tumor cells." (PMID 17177999, 2006). "Interleukin-6 is the main inducer of the APPR in human hepatocytes and both IL-1β and TNF-α are capable of inducing IL-6 production from both tumour and host cells." (PMID 17088911, 2006). "For example, TNF-α can induce apoptosis in tumour cells of the colon and its cytotoxic effect is synergistically enhanced by IFN-γ in vitro and in vivo." (PMID 16641913, 2006). "Tumour proliferation and apoptosis correlate to progressive suppression of the CMI-associated cytokine TNF-α and to and higher levels of IL-10." (PMID 16641913, 2006). "TNF, IL-6, and IL-8 can directly or indirectly promote tumor growth via induction of VEGF expression." (PMID 17096856, 2006). "mRNA levels of TNFα and IL-6 were unchanged in tumour-bearing mice compared with controls (both P>0.05)." (PMID 17047651, 2006). "In contrast, mRNA expression of TNF-α in the liver around the tumour was comparable with normal and sham-operating liver." (PMID 15841081, 2005). "Neoplastic disease often creates a thrombogenic state, through inflammation mediators, tumor necrosis factor, platelet activation, as well as a procoagulant substances released by tumor cells." (PMID 16111500, 2005). "Following a short course of TNF-α, the nuclei of tumour cells became intensely stained with the anti-p65 antibody indicating the translocation of NF-κB from the cytoplasm to the nucleus." (PMID 16278667, 2005). "It is interesting that the selective procoagulant and permeability effects of TNF, a cytokine with broadly overlapping biological activities with IL-1, on tumor neovasculature have been applied in the clinical treatment of cancer." (PMID 16197553, 2005). "Abundant expression of TNF-α mRNA in primary tumour of orthotopically implanted CBO140C12 cells in the liver support the idea that TNF-α-meidated cellular activities are potential targets for the antimetastatic activity of gefitinib." (PMID 15841081, 2005). "It has been demonstrated that inflammatory cytokines including TNF-α play critical roles in tumour metastasis." (PMID 15841081, 2005). "In several tumour cell lines, TNF-α induced the expression of several different adhesive molecules including several integrin subunits, ICAM-1 and VCAM-1." (PMID 15841081, 2005). "Inhibition of NF-κB activity either pharmacologically or genetically can sensitize tumor cells to pro-apoptotic agents or to tumor necrosis factor-α (TNF-α) induced apoptosis." (PMID 16332260, 2005). "In contrast, when TC and T18 cells were induced to apoptosis with TNF-α, only caspase 8 inhibitor inhibited tumor cell apoptosis." (PMID 15907209, 2005).
tumor (continued). "Real-time reverse transcription–polymerase chain reaction showed that TNF-α mRNA was expressed in large quantities in the implanted tumour." (PMID 15841081, 2005). "Blood flow in tumours implanted in TNF−/− and TNFR−/− mice was determined from Hoechst-stained vessels, and was, respectively, 2.5- and 5.3-fold lower than that in tumours in wild-type mice, 3 h following DMXAA at 25 mg kg−1." (PMID 14970872, 2004). "Previous studies have suggested that one of the main mechanisms by which TNF promotes tumour growth is by upregulating metastasis." (PMID 15026813, 2004). "Studies have also shown that, a higher anti-tumor effect and lower toxicity were got by modified some structure of TNF." (PMID 15485573, 2004). "Interleukin-6 (IL-6) and tumour necrosis factor-alpha (TNF-α) are important multifunctional cytokines involved in tumour growth and metastasis." (PMID 15150588, 2004). "Tumour endothelial cell apoptosis in TNF−/− and TNFR−/− hosts following DMXAA (25 mg kg−1) was, respectively, 1.8- and 10.4-fold lower than that in wild-type mice." (PMID 14970872, 2004). "In this report we show that mithramycin considerably increases the direct cytotoxic effect of tumour necrosis factor (TNF) on tumour cells in vitro." (PMID 15138489, 2004). "It has been well shown in vivo or in vitro that TNF assists anti-tumor treatment and intensified the sensitivity of chemotherapy to many different kinds of tumor cells." (PMID 15485573, 2004). "Given the importance of dendritic cells for the initiation of anti-tumor immune responses and as a source of IL-12 and TNF-α we tested the capacity of recombinant PstS1 to activate human monocyte-derived dendritic cells." (PMID 15566565, 2004). "The finding of a rapid onset of tumour endothelial apoptosis, occurring before the appearance of detectable TNF in tumour tissue, suggests that DMXAA exerts a direct effect on tumour vasculature, and is of particular relevance to clinical trials." (PMID 14970872, 2004). "TNF is induced following DMXAA administration to mice, and the histology of tumours treated with DMXAA resembles that of TNF-treated tumours, suggesting that TNF participates in the antivascular action." (PMID 14970872, 2004). "Past studies suggested that tumor necrosis factor (TNF) assisted anti-tumor treatment and intensified the sensitivity of chemotherapy." (PMID 15485573, 2004). "Second, most of the TNF tumour-promoting effects that have been described concern processes that occur during metastasis." (PMID 15026813, 2004). "They suggested that macrophages secreted TNF-alpha and IL-1, which in turn stimulated tumour cells to produce IL-8 and VEGF, the latter cytokine then inducing angiogenesis." (PMID 14970860, 2004). "As TNF autovaccination requires 4–6 weeks to induce optimal TNF autoantibodies, the tumour burden by that time would have been too great, with many mice already dead or in great pain for the procedure to be ethically acceptable." (PMID 15026813, 2004). "Apoptosis was significantly lower in Colon 38 tumours of mice, with a targeted disruption in the TNF gene (TNF−/−), or in the TNF receptor 1 gene (TNFR−/−), as compared with that in wild-type mice." (PMID 14970872, 2004). "In vivo, some cancers particularly epithelial tumours produce TNF; however, in other cancers, stromal cells are a source of TNF that can then have an effect on the tumours." (PMID 15026813, 2004). "DMXAA also increased tumour necrosis factor (TNF) concentrations in both plasma and tumour tissue of mice." (PMID 14970872, 2004). "They suggested that macrophages secreted TNF-alpha and IL-1, which in turn stimulated tumour cells to produce IL-8 and VEGF, the latter cytokine-inducing angiogenesis." (PMID 14970860, 2004). "For this, we examined the effect of treating mice with anti-TNF monoclonal antibodies upon tumour insertion and had a reduction in the lung metastases compared to the PBS-treated control group." (PMID 15026813, 2004).
tumor (continued). "Mutant 471 had a 7-fold higher anti-tumor activity against murine L-M cells in vitro, and a higher binding activity to TNF receptors on L-M cells, than wild-type TNF." (PMID 15485573, 2004). "So in vitro tumour cells were exposed to a range of TNF-α concentrations varying from 0 to 10 μg ml−1." (PMID 12610519, 2003). "BAb+TNFα+RT combination enhanced the delay for the tumour to reach 1500 mm3 as compared with RT alone or with RT+TNFα (P=0.0011)." (PMID 14612914, 2003). "The authors constructed, also, a TNF-Selectokine prodrug by insertion of a TNFR1 fragment separated from TNF by a protease-sensitive linker in order to restrict TNF activity to the tumour." (PMID 14612914, 2003). "We found that TNF-α-mediated DNA fragmentation in tumour cells was significantly reduced in the presence of E64d and CA074Me, two inhibitors of lysosomal cysteine proteases." (PMID 14562034, 2003). "This indicates that TNF-α has specific tumour vascular mediating capacity in this perfusion model, which results in enhanced tumour responses in highly vascularised tumours." (PMID 12610519, 2003). "In the present study, the in vitro growth-inhibitory effect of TNFα was accompanied by a marked enhancement of the radioresponse of the tumour in vivo, particularly, when TNFα was concentrated in the tumour xenografts thanks to our BAb." (PMID 14612914, 2003). "Especially, Cath-B has been suggested to play an essential role in TNF-mediated apoptosis, and has been proposed to represent a therapeutical target in cancer therapy of tumours with elevated levels of cysteine proteases." (PMID 14562034, 2003). "The response rate in BN-175 tumour-bearing rats when TNF-α was coadministrated with melphalan was strongly correlated with drug accumulation in tumour tissue, as only in these rats a five-fold increased melphalan concentration was observed." (PMID 12610519, 2003). "Using nude mice-bearing BxPC-3 xenografts, we showed a significant enhanced tumour growth delay when the BAb+TNFα+RT combination was used as compared with RT alone and with RT+TNFα." (PMID 14612914, 2003). "When IHP was performed in BN-175-bearing rats with the combination of melphalan and TNF-α, a dramatically enhanced tumour response was observed in all animals." (PMID 12610519, 2003). "Assessment of the tumour vasculature of liver metastases would be a way of establishing an indication for the utility of TNF-α in this setting." (PMID 12610519, 2003). "BxPC-3 tumours growing s.c. in the right flank of nude mice were used to test the antitumour activity of TNFα alone or in combination with RT." (PMID 14612914, 2003). "It must be noted, however, that TNF-α can elicit a wide variety of biological responses in both normal and tumour cells." (PMID 12966436, 2003). "During the same period of observation, treatment with TNFα slowed tumour growth in irradiated groups, particularly when TNFα was coinjected with BAb." (PMID 14612914, 2003). "In the control group and the groups treated with TNFα, BAb, or BAb+TNFα, the median delay for the mice to reach a tumour volume greater than 1500 mm3 was 62, 62, 65, and 62 days, respectively, with no statistical difference between the groups." (PMID 14612914, 2003). "In the present study, we demonstrated that addition of TNF-α to IHP with melphalan results in strongly improved response rates in a tumour with high vascular density." (PMID 12610519, 2003). "Only the ROS-1 tumour cells were moderately sensitive to TNF-α, a growth inhibition of up to 30% at 10 μg ml−1 was observed." (PMID 12610519, 2003). "At day 93, when mice in all other groups were killed (tumour >1500 mm3), the median value of the tumour volume was 260 mm3 for the RT+BAb+TNFα group." (PMID 14612914, 2003). "5,6-Dimethylxanthenone-4-acetic acid (DMXAA), a new analogue of FAA developed in the ACSRC, showed greater activity and 12-fold higher dose-potency than FAA in murine tumour models and appeared to overcome the species difference in in vitro TNF production." (PMID 12799625, 2003).
tumor (continued). "This is a significant reduction of mean tumour volume compared with rats perfused with either TNF-α only or melphalan alone (P<0.005 and <0.01, respectively)." (PMID 12610519, 2003). "Several studies have demonstrated the antitumour activity of RT+TNFα, but this treatment was given before the tumours reached a palpable volume, making a comparison with our results difficult." (PMID 14612914, 2003). "Our data demonstrate the interest of targeting TNFα to tumours to improve RT and finally to keep a large differential effect between tumour and normal tissues." (PMID 14612914, 2003). "Here we present data that indicate that the antitumour effect of TNF-α is correlated with the tumour microvessel density." (PMID 12610519, 2003). "Various methods have recently tried to concentrate TNFα into tumour such as Cu2+-dextran, TNFα-biotin conjugates, or liposomal encapsulated-TNFα which are less specific targeting than our BAb and were not tested with concomitant radiotherapy." (PMID 14612914, 2003). "The tumour-promoting effect of cathepsins is in contrast to the observation that cathepsins such as Cath-B can mediate proapoptotic signals triggered by TNF, bile salts, sphingosine, activation of the B-cell receptor, and L-2,5-dihydrophenylalanine." (PMID 14562034, 2003). "Studies on the effects of TNF-α using experimental models of invasion and metastasis have shown that it can often act as a tumour-promoting factor." (PMID 12966436, 2003). "Assessment of the degree of tumour vasculature of liver metastases would be a way of establishing an indication for the utility of TNF-α in this setting." (PMID 12610519, 2003). "Repeat dosing at 3- or 7-day intervals produced greater induction of TNF-α and growth delay in colon 38 tumours in mice than a single dose of DMXAA." (PMID 12698178, 2003). "Recent studies suggest that TNFR1-expressing endothelial cells of the tumour vasculature are the targets of TNF-induced necrosis." (PMID 12177785, 2002). "Administration of TNF and actinomycin D in mice delayed the growth of several tumours significantly, but application was limited due to the severe toxic effects." (PMID 11953868, 2002). "It is an interesting drug to evaluate in combination with TNF because incubation of tumour cells with actinomycin D has been shown to increase their sensitivity to the effects of TNF." (PMID 11953868, 2002). "DMXAA also induced TNF synthesis in host cells, and in some cases tumour cells, of a series of human tumour xenografts." (PMID 12085190, 2002). "Previously we have demonstrated that local treatment of advanced tumours with a combination of melphalan and TNF results in high response rates." (PMID 11953868, 2002). "In situ hybridisation studies indicate that both host and tumour cells within murine colon 38 tumours express TNF mRNA after DMXAA treatment." (PMID 12177785, 2002). "Rats treated with a combination actinomycin D and TNF showed again massive infiltration of red blood cells and haemorrhagic necrosis in tumour." (PMID 11953868, 2002). "It induced TNF synthesis in both host and tumour cells of Colon 38 tumours and also induced significant amounts of TNF in murine Colon 38 tumours implanted in TNF knockout mice." (PMID 12085190, 2002). "One of the most unusual properties of DMXAA is its ability, as a low molecular weight drug, to induce the cytokine TNF in both plasma and tumour tissue." (PMID 12177785, 2002). "At 5 days after ILP a significant difference in the mean tumour volume was observed as compared to sham perfusions (P<0.05), TNF perfusions alone (P<0.05) and actinomycin D perfusions alone (P<0.05)." (PMID 11953868, 2002). "The tumour conditioned medium had a greater effect on endothelial cells than did hypoxia, reduced oxygen tension, TNF, FAA or DMXAA, providing another clear example of the priming effect of tumour secreted factors." (PMID 12085190, 2002).